PPARG (peroxisome proliferator activated receptor gamma)
Diseases named in the same sentence as PPARG in open-access papers (continued):
Sharing a sentence is not in itself a finding about the gene and the disease.
Obesity (continued). "Further studies are needed to establish individual associations between PPARG allelic variants and obesity." (PMID 37761915, 2023). "Collectively, our study demonstrates PPARγ acetylation in adipose tissue as a pathogenic factor underlying metabolic dysfunction in aging and obesity." (PMID 37408258, 2023). "As such, PPARγ has been implicated as a determinant of longevity; however, how PPARγ is dysregulated in aging and how that ties into its deregulation in obesity remains poorly understood." (PMID 37408258, 2023). "In a cohort of Northwest Mexican adults, single-nucleotide polymorphisms (SNPs) in the ABCA1 gene as well as FTO alpha-ketoglutarate-dependent dioxygenase (FTO), adrenoceptor beta 3 (ADRB3), and PPARG were associated with increased risk of obesity." (PMID 38027204, 2023). "Activation of PPARγ by capsaicin has also been associated with its beneficial action on obesity, reducing inflammatory markers and inducing the expression and synthesis of adiponectin in mouse adipocytes." (PMID 37892544, 2023). "PPARγ is a nuclear receptor that is associated with obesity and metabolic diseases by converting adipocytes from their precursors." (PMID 37244925, 2023). "Peroxisome proliferator-activated receptor-γ (PPARγ) is inhibited and adipogenesis is suppressed during adult obesity and the loss of adiponectin." (PMID 37233716, 2023). "All these findings support that GN is an ED that is capable of causing obesity through interacting with the PPARγ protein." (PMID 38098865, 2023). "Another polymorphism, C478T, within the PPARγ gene, has been associated with higher leptin levels in individuals living with obesity, and it has been linked to obesity and an increased fat mass in women." (PMID 37571382, 2023). "PPARG is a key regulator of adipocyte differentiation and is also closely associated with obesity, diabetes, atherosclerosis and cancer." (PMID 38074668, 2023). "To explore the mechanisms underlying the protective effects of TGFBI during obesity, we examined the PPARγ signaling pathway, which is closely involved in adipocyte differentiation, in iWAT from ND- and HFD-fed WT and TGFBI KO mice." (PMID 36854775, 2023). "Afterward, based on TFEA and qRT-PCR verification, we confirmed that SOCS3, ICAM-1, NT5E, MYC, CCL2, and PPARG were potential ORDEGs that linked obesity and OLF pathogenesis." (PMID 35712246, 2022). "The PPARG Pro12Ala genotype is associated with susceptibility to obesity; however, the observed effects of its presence in an individual’s genotype are highly dependent on that individual’s lifestyle." (PMID 36558537, 2022). "Several studies conducted on the adult population showed a positive association between PPARG Pro12Ala polymorphism (rs1801282) and obesity in adults, ultimately proving the involvement of the variant G allele." (PMID 36466447, 2022). "PPARγ is beneficial for promoting mitochondrial biogenesis and inhibiting ER stress, a prominent feature associated with diabetes, obesity, and chronic inflammation." (PMID 36213491, 2022). "In humans, variations that produce constitutively effective PPARγ (the genetic alternative of TZD application) result in grave obesity while dominant negative PPARγ variation causes partial lipodystrophy." (PMID 36295635, 2022). "Hypoxic treatment was previously shown to aggravate endothelial damage by down-regulating the PPARγ pathway in the leptin receptor deficient db/db mice, which are used to model obesity and insulin resistance." (PMID 36147493, 2022). "Apparently, a moderate reduction of PPARγ activity, observed in heterozygous PPAR γ-deficient mice or in the Pro12Ala polymorphism in human PPARγ protein, has been shown to prevent insulin resistance and obesity induced by a high-fat (HF) diet." (PMID 36501129, 2022). "By using a computational analysis of SNPs in PPARG, researchers found that mutations in PPARG impaired functions of PPARγ, leading to serious complications such as obesity, diabetes, and cancer in humans." (PMID 35402540, 2022).
Obesity (continued). "By utilizing this model, we show that macrophage PPARγ Lys293 acetylation is a causal factor involved in deteriorating adipose tissue integrity during obesity." (PMID 37213714, 2022). "The aberrant PPARγ signaling pathway was associated with the development of obesity, diabetes, and cancers." (PMID 36587194, 2022). "We found that obesity was associated with lower PPARγ expression in lung tissues and its level further decreased during ALI." (PMID 36213491, 2022). "A previous study on unrelated German subjects demonstrated that the PPARG Pro115Gln (rs1800571) missense variant is possibly pathogenic for severe obesity." (PMID 36466447, 2022). "PPARγ is an interesting target because of its association with disorders such as atherosclerosis, diabetes, obesity, and cancer." (PMID 36358965, 2022). "This was supported by a cross-sectional study conducted among Malay adults demonstrating that the Pro12Ala of the PPARγ gene was closely associated with obesity, as shown by the Ala12 carriers had a significantly higher BMI." (PMID 36551995, 2022). "Mutations in the PPARG gene have been associated with diseases such as atherosclerosis, diabetes, and obesity." (PMID 36532520, 2022). "Higher PPARA and PPARG methylation levels were observed in association with obesity, consistent with decreased PPAR-α and PPAR-γ protein expression levels, that lead to dyslipidemia and IR." (PMID 35794109, 2022). "Further, obesity, hypertension, and smoking are observed to be the most critical risk factors accompanying Pro/Ala mutation in peroxisome proliferator-activated receptor gamma (PPAR-γ), thus are associated with a high risk of DM." (PMID 35767589, 2022). "Upon obesity, such as in leptin-deficient (ob/ob) mice, PPARγ and its target gene Fsp27 are activated in the liver to promote FA storage as lipid droplets." (PMID 36172518, 2022). "Although we demonstrated that genetic variants on ESR1 and PPARg locus are associated with severe obesity (BMI > 35) in Han Chinese individuals, their associations with mild to moderate obesity (BMI in the range of 27.0 to 34.9) were not tested." (PMID 36297109, 2022). "Another gene peroxisome proliferator activated receptor gamma was suggested to cause obesity, a common comorbidity of BPH." (PMID 36059933, 2022). "The activation of PPARγ by PPARγ agonists is a lipolytic mechanism protective against kidney changes caused by obesity." (PMID 35629966, 2022). "Other studies suggest that the presence of certain alleles in the PPARG gene can lead to obesity, insulin resistance, and type 2 diabetes or metabolic syndrome." (PMID 36558537, 2022). "The target was the protein regulating gene peroxisome proliferator-activated receptor gamma (PPARg), which has been linked to several diseases such as obesity, diabetes, atherosclerosis, and cancer." (PMID 35902962, 2022). "Investigations of the association of CD24 with obesity and weight gain in humans should consider the distribution of the single nucleotide polymorphisms (SNPs) of PPARγ, including gender-dependent associations in this regard." (PMID 33467499, 2021). "Compared with the normal Pro allele, the Ala-substituted allele leads to a reduction in activity of PPARγ, which can be a high-risk factor for the occurrence of obesity and type 2 diabetes." (PMID 34685423, 2021). "In previous studies, genetic variants in the FTO (fat mass and obesity-associated) and PPARγ (peroxisome proliferator-activated receptor-gamma) genes have been associated with metabolic disease, body mass index, and obesity among other outcomes." (PMID 33729310, 2021). "Transcriptome data revealed that Arid5a binds to the promoter region of Pparγ, which is the leading cause of adipogenesis, and represses the transcription of the Pparγ gene, thereby inhibiting adipogenesis and obesity in mouse fibroblasts." (PMID 35126382, 2021). "Hyperexpression of PPARγ is associated with obesity in humans, and PPARγ expression is also correlated with fat deposition in broilers." (PMID 32810939, 2021).
Obesity (continued). "These M2-like macrophages are beneficial as PPARγ and PPARδ-deficient mice, which have impaired M2 polarisation, are more prone to diet-induced obesity, inflammation and insulin resistance." (PMID 34613819, 2021). "Multiple reports have linked variants of PPARγ with diseases such as coronary heart disease, cancer, metabolic syndrome, and especially obesity and diabetes." (PMID 34685423, 2021). "PPARG is primarily expressed in adipose tissue, has a role in regulation of adipocyte differentiation, and has been associated with risk for obesity and T2DM." (PMID 34425916, 2021). "The present study reports the molecular mechanisms underlying the anti-obesity and glucose-lowering effects of VS extract by regulating C/EBPα-mediated lipogenesis, PPARα-mediated fatty acid β-oxidation, and PPARγ-mediated insulin sensitivity." (PMID 33671428, 2021). "In summary, our data demonstrate that the obesity caused by Crtc1–/– deficiency was associated with increased fat accumulation in white adipose tissues, which potentially via activating PPARγ signaling pathway." (PMID 33912553, 2021). "Proposals to target EZH2–HDAC9c interaction for the treatment of age-associated osteoporosis and obesity are supported by the report that HDAC9c attenuates adipogenesis by interfering with PPARγ transcriptional activity." (PMID 34638914, 2021). "Peroxisome proliferator activated receptor gamma (PPARG) encoded a protein called PPARγ, which regulates adipocyte differentiation and has been implicated in the pathology of many diseases, including obesity, diabetes, atherosclerosis and cancer." (PMID 33912166, 2021). "Meanwhile, PFAS-induced activation of PPARγ can lead to adipogenesis and inflammation, contributing to increased adiposity and risk of obesity in children and adolescents." (PMID 34566884, 2021). "This is significant because myeloid cell-specific disruption of PPARγ and/or PPARδ increases pro-inflammatory activation of adipose tissue macrophages and exacerbates obesity-associated IR." (PMID 34943809, 2021). "SERPINE1 is a unique insulin-sensitizing adipocytokine and, like PPARG, is implicated in a wide range of metabolic diseases, including DM, obesity, and fatty liver diseases." (PMID 35052729, 2021). "While upregulation of PPARγ expression is linked to obesity, activation of this receptor has also been shown to enhance insulin sensitivity and accelerate blood triglyceride clearance, hence preventing insulin resistance and hypertriglyceridemia." (PMID 34072832, 2021). "Genetic variants in the FTO (fat mass and obesity-associated) and PPARγ (peroxisome proliferator-activated receptor-gamma) genes are known to be associated with the incidence of metabolic disease, body mass index and obesity." (PMID 35008459, 2021). "Due to its role in lipid and carbohydrate metabolism, the PPARG gene is often described as a candidate gene associated with obesity and other obese phenotypes." (PMID 34828287, 2021). "Few studies have also reported the relationship between PPARG polymorphisms and the risk of obesity or psychiatric disorders in patients treated with olanzapine or clozapine." (PMID 33240378, 2020). "For example, the programming of adipose tissue of rat pups exposed to in utero under-nutrition or maternal obesity seems associated with early induction of the adipogenic transcription factor PPARγ, whose activation leads to adipocyte differentiation." (PMID 31991777, 2020). "Several studies which reported mutations in the PPARγ protein were related to some diseased states; for example, PPARγ P115Q results in severe obesity, and P467L and V290M mutations are partially involved in familial lipodystrophy type 3." (PMID 32158560, 2020). "Due to its wide-spectrum of regulatory effects, mutations in PPARγ have been identified in the humans and led to dysfunctional lipid and glucose metabolism, insulin resistance, which developed into obesity-induced T2DM, dyslipidemia, NAFLD, and cancer." (PMID 32158560, 2020).
Obesity (continued). "To date, PPARγ is the only modulator of adipogenesis that has shown clinical relevance in addressing an obesity associated comorbid condition like diabetes." (PMID 32560163, 2020). "Repressive PPARγ modulators acting as inverse agonists are suggested as promising therapeutic options in obesity management and are associated with enhancement in bone formation and improved WAT metabolic functions." (PMID 33371201, 2020). "Differences of selected variants on obesity risk among the two populations were fairly modest, except PPARγ’s protective effect on central obesity among Roma subjects." (PMID 32384785, 2020). "According to in silico analysis of transcription factor binding sites, the promoter regions of miR-96-5p contain putative binding sites for various transcription factors associated with adipogenesis and obesity, such as SREBPs, PPARγ, and C/EBPα." (PMID 33322515, 2020). "We have previously shown that miR-27b can repress PPARγ and lipid metabolism-associated factors, thereby affecting lipid metabolism during hypoxic exercise in a rat model of obesity." (PMID 32982800, 2020). "Findings for Srebp1c mRNA expression as well as PPARγ activity and expression in liver are somewhat contrasting the findings of others reporting that in settings of high-fat diet/ obesity-associated NAFLD, these nuclear factors are found to be increased." (PMID 32881925, 2020). "Obesity is the strongest risk factor for the development of OSA, and PPARG plays an important role in the development of obesity." (PMID 31044373, 2020). "In particular, PPARγ plays a key role in adipogenesis and has been implicated in the pathology of numerous diseases including obesity, type 2 diabetes, and atherosclerosis." (PMID 33313321, 2020). "Secondly, the activation of PPARγ improves insulin sensitivity and blood glucose homeostasis, which is used for the treatment of obesity-associated diabetes in humans." (PMID 32102233, 2020). "The chronic inflammatory state of obesity is associated with excessive production of TNFα, which downregulates PPARγ expression." (PMID 33841133, 2020). "In a context of obesity, such a modulation of PPARγ expression represents a very interesting therapeutic angle to reduce obesity-associated WAT pathological remodeling." (PMID 33003504, 2020). "The PPARG rs1801282 polymorphism has attracted much attention because of its correlation with various metabolic conditions including obesity, diabetes, and dyslipidemia." (PMID 31044373, 2020). "PPARγ has been implicated in the pathology of numerous diseases including obesity, diabetes, hypertension, and cancer; it also plays a key role in the pathological process of PH." (PMID 31703458, 2019). "Obesogens can cause obesity through direct activation of PPARγ, but other mechanisms involve indirect activation of the receptor by increasing the PPARγ protein and making it available to promoters of genes in the adipogenic pathway." (PMID 31500194, 2019). "Mutations in PPARγ lead to dysfunctional lipid and glucose homeostasis and have been directly related to type 2 diabetes mellitus and obesity, familial partial lipodystrophy type 3 (FPLD3), and also cancer." (PMID 30012954, 2018). "Studies have shown that a transient overexpression of C/ebpα and Pparγ would induce remodeling of the fat issue, while long-term overexpression would result in the occurrence of diabetes and obesity, both of which are risk factors of KOA." (PMID 29670657, 2018). "Two studies showed that macrophage-specific deletion of PPARγ predisposes mice to development of diet-induced obesity and insulin resistance." (PMID 29799467, 2018). "PPARγ is a member of nuclear receptors that regulate the transcription of several genes associated with obesity and diabetes." (PMID 30445764, 2018).
Obesity (continued). "T cell-specific actions of PPARs, in the context of atherosclerosis or obesity-associated inflammation and insulin resistance, have largely been unexplored, with the exception of the role of PPARγ in adipose tissue Tregs in the latter." (PMID 29799467, 2018). "The BPro12Ala and 6CAC478CAT exon polymorphisms of the PPARγ gene are significantly related to the incidence of severe obesity." (PMID 30034368, 2018). "Conversely, increased expression of PPARγ protects from the insulin resistance associated with obesity." (PMID 30037087, 2018). "The researchers discovered that Gleevec blocks CDK5-mediated PPARγ phosphorylation, and thus lowers the level insulin resistance and reduces the risk of hyperglycemia and obesity." (PMID 29385209, 2018). "This suggests that DNA methylation of the PPARγ promoter can inhibit the expression of the PPARγ gene and is associated with the occurrence of obesity and diabetes." (PMID 30034368, 2018). "We did not detect statistical associations between LEPR rs11371101, FTO rs9939609, MC4R rs2229616, and PPARG-2 rs1801282 polymorphisms and most obesity-related phenotypes and metabolic parameters." (PMID 29679223, 2018). "Previous studies have reported that hepatic steatosis is associated with elevated PPARγ expression in models of diabetes or obesity." (PMID 30061831, 2018). "To explore the molecular mechanisms underlying CD38 deficiency‐mediated inhibition of obesity, we detected the protein expression levels of Sirt1 and the target gene PPARγ which was known to promote adipocyte differentiation." (PMID 28816006, 2018). "The PPARG rs1801282 variant is positively associated with obesity and has been extensively examined in epidemiological studies." (PMID 29679223, 2018). "Although the association between genetic variants of the PPARG gene and obesity traits has been widely studied, as far as we know there is limited evidence regarding the relationship between PPARA variants and obesity phenotype." (PMID 29795275, 2018). "In clinic, the full PPARγ agonists TZDs are very effective in glycemic control but have multiple adverse effects such as obesity, water retention, and increased risk of cardiovascular diseases and bone fractions." (PMID 30186237, 2018). "Consistent with the role of PPARγ in glucose and lipid homeostasis, an abnormal activity of PPARγ is often associated with the development of metabolic disorders (e.g., obesity, type 2 diabetes, and fatty liver disease)." (PMID 28167956, 2017). "In summary, ZIP14 showed a close inverse relationship with anthropometric markers of obesity as well as a positive association with the adipose expression of PPARG." (PMID 28303117, 2017). "PPARG has been implicated in the development of various diseases involving obesity, diabetes, inflammation, atherosclerosis and cancer." (PMID 29254243, 2017). "Loss of BCO1 expression has been linked to obesity and lipid metabolism and lipid accumulation in adipocytes by modulating PPARγ and RAR signaling pathways, although remains uncertain if BCO1 affects lipid metabolism in a similar manner in different tissues." (PMID 28732066, 2017). "We concluded that curcumin has the potential to improve glycolipid metabolism disorders caused by obesity through regulating PPARγ signalling pathway." (PMID 29291086, 2017). "One such example is PPARG, a gene found to be associated with T2D and monogenic forms of severe obesity and severe digenic insulin resistance." (PMID 28073971, 2017). "To investigate the mechanisms underlying the anti-obesity effects of GL and DL, we measured the mRNA and protein expression of adipogenesis-related genes such as the key adipogenic regulators C/EBPα and PPARγ." (PMID 28891956, 2017). "We employed the GMDR analysis to assess the impact of the PPARG gene- obesity interaction on T2DM risk, after adjustment for gender, age, smoke and alcohol consumption status, high fat diet, low fiber diet, TC and HDL." (PMID 28123453, 2017).